NOTCH1 (notch receptor 1)
Diseases named in the same sentence as NOTCH1 in open-access papers (continued):
Sharing a sentence is not in itself a finding about the gene and the disease.
cancer (continued). "However, the lack of correlation between Notch pathway compounds, clinical characteristics and outcome does not support their use as biomarkers.We observed that Notch3 is expressed in cancer cells, whereas Notch1 is mainly expressed in blood vessels." (PMID 22074495, 2011). "To further test this possibility, we determined the minimal functional region of the Notch1 promoter and assessed whether such region is differentially active in normal versus cancer cells." (PMID 20442780, 2010). "Equivalent missense mutations in human Notch1 cause T-ALL and perhaps other cancers." (PMID 20686701, 2010). "Notch1-dependent proliferation has been previously reported in some cancer cell lines." (PMID 20161710, 2010). "Additionally, Notch1/Hes1 signaling pathway participates in EMT of cancer cells." (PMID 38166853, 2024). "It was proposed previously that Notch1 might be oncogenic for many cancer cells." (PMID 40034926, 2024). "Moreover, it was proposed previously that Notch1 might be oncogenic in various types of cancer, but the question arises as to why many SCLC cell lines do not express this pathway." (PMID 40034926, 2024). "An association of NOTCH1 loss of function mutation with TAP1 dependency was present but of unclear significance given that the TAP1 gene product's role in antigen presentation is not predicted to impact cancer cell line viability or growth in standard culture." (PMID 37997254, 2024). "Therefore, targeting the USP10–N1ICD interaction could be a potential antitumor strategy for Notch1-hyperactivated cancers." (PMID 37714834, 2023). "Of interest, recent evidence pinpoints a synergistic function of TLR9 and Notch1 in driving the metabolic adaptation for populating cancer stem-like cells, indicating that ALD-DNA-induced TLR9 and Notch1 signaling might drive metabolic adaptation in macrophages." (PMID 37626904, 2023). "Furthermore, through expression of ligands for Notch and Bmp7, tuft cells could target Notch1/3 and Endoglin (Eng) on endothelial and smooth muscle cells to promote cancer progression through promotion of angiogenesis." (PMID 37386128, 2023). "Given that metabolic reprogramming is an essential mechanism of cancer cell outgrowth and dissemination, understanding the multiple levels of interconnections between NOTCH1 and metabolic pathways may help to delineate novel strategies to tackle exacerbated metabolic demand in T-ALL." (PMID 36674902, 2023). "Indeed, Notch1-mediated prolonged nuclear retention of p65 can explain our data showing that although NF-κB alone can induce MenaINV expression (1.5-fold), the level of induction is below the one achieved by macrophage-cancer cell contact (5-fold)." (PMID 37024946, 2023). "Therefore, we speculate that the Notch1 signaling pathway may be responsible for cancer resistance and recurrence during malignant progression." (PMID 37533228, 2023). "Strategies that target Notch genes, such as Notch 1, may prove beneficial for cancer treatment." (PMID 37305676, 2023). "Therefore, we hypothesized that small molecules that promote the degradation of Notch1 or interfere with its transcriptional complex could be a promising alternative strategy to target Notch1-activated cancers." (PMID 37714834, 2023). "Other miRNAs are implicated in the activation of cancer development such as miR-19 and miR-501-5p through activating wingless (WNT)/β-catenin signaling pathway, and miR-483-5p, miR-196b-5p and miR-494-3p through activating the cyclin D1, STAT3, and Notch1 signaling pathways." (PMID 35327559, 2022).
cancer (continued). "The effects of SMAD3 and Notch1 are almost the same in cancer cell migration, as knockdown of either of the two could decrease the migration advantage seen in the overexpression of NUMB-p66, and overexpression could rescue the migration reduction seen in p65/p66 knockdown." (PMID 35457181, 2022). "Additionally, Notch1 signaling plays a role in the features of cancer stem cells." (PMID 36183290, 2022). "Notch1 inhibition may possess potential benefits in clinical cancer therapy." (PMID 35723384, 2021). "Indeed, FAT1, CASP8, CDKN2A, and NOTCH1 mutations were found more frequently in these tumors compared with other HNCs malignancies and other squamous non-HNCs cancers." (PMID 34440249, 2021). "Similarly, the intracellular domain of the transmembrane glycoprotein CD147 (ICDs) regulates Notch1 expression by direct binding to the NOTCH1 promoter and induces the activation of the Notch signaling pathway resulting in cancer cell proliferation via Notch1 signaling." (PMID 33804511, 2021). "In addition, HNSCC cancer cases have been identified that clearly show amplification of the NOTCH1 locus on chromosome 9, in conjunction with over-expression of NOTCH1 mRNA and protein." (PMID 34944837, 2021). "It is now considered that generalized activation of downstream Notch signalling may promote late-stage cancer progression, regardless of frequent NOTCH1 mutations, which show an overwhelming negative functional impact." (PMID 34944837, 2021). "Interestingly, there is data indicating that there might be a link between miR-34a and NOTCH1 expression, with respect to cancer stemness." (PMID 32047551, 2020). "Because NOTCH1 LOF mutations are common in other SCCs, including those of skin, esophagus, cervix, and lung, these findings may have implications for the treatment of cancers beyond HNSCC." (PMID 33322834, 2020). "Therefore, our data support the speculation that FEZF1-AS1 may sponge miR-34a to up-regulate NOTCH-1, thereby promoting the invasion and migration of cancer cells." (PMID 32349744, 2020). "Additionally, the Wnt/β‐catenin pathway participates in cancer malignant behaviours by interacting with other signalling pathways including Notch1/3,31, 32 Hippo, nuclear factor‐κB,4 and extracellular signal‐regulated kinase 1/2,34 all of which were reported to have dual effects on autophagy." (PMID 31111621, 2019). "Interestingly, some studies showed a Notch1 involvement in metabolic alterations of cancer cells." (PMID 31379945, 2019). "Thus, it appears that a cancer is substantially more likely to initiate in a clone without a Notch1 mutation (as well as for other mutations, but we will use Notch1 mutation as the prototype here)." (PMID 30848555, 2019). "Mutations of FBXW7 and NOTCH1, which could lead to aberrant activation of Notch signaling pathway, were only detected in patients without germline cancer-associated variants." (PMID 30850667, 2019). "Curcumin has been shown to play an anti-cancer effect in OS cells, its mediation can potentially be occurred via Notch-1 signaling inactivation, suggesting that curcumin is involved in upregulation of Notch-1 may be considered as a potential therapeutic strategy for OS." (PMID 30349420, 2018). "However, because of its role in mediating signaling events from other proteins, with a primary focus on NOTCH1 signaling, γ‐secretase has become a therapeutic target in cancer and immunologic diseases and may very well be a target in other conditions." (PMID 28539479, 2017). "Notably, we found the over-expression of Notch-1 could abrogate the anti-cancer function induced by rottlerin." (PMID 28977931, 2017). "Interestingly, a significant positive correlation between Notch-1 and Syndecan-1 mRNA levels (r = 0.793, P = 0.001) and between Notch-3 and Syndecan-1 mRNA levels (r = 0.819, P = 0.001) did exist in carcinoma tissues of IBC." (PMID 28270211, 2017).
cancer (continued). "Nakajima and colleagues had described a galectin-3-dependent activation of Notch1 signaling in a system that models tumor cell/osteoblast and osteoclast interactions, critical events in the maintenance of bone metastasis found in different cancers, such as breast and prostate cancers." (PMID 27242966, 2016). "Furthermore, the suppression of cancer progression by Notch1 knockdown could be rescued by miR-151 overexpression." (PMID 27191259, 2016). "Furthermore, Notch1 expression correlates with disease progression, with little or no protein expression in normal cervical epithelium and high expression in precancerous and cancer tissues." (PMID 25309874, 2014). "However, little information on visfatin-Notch1 interactions in cancer is available." (PMID 24970818, 2014). "In addition to cancer cells, we observed widespread activation of NOTCH1 in normal endothelial cells and variable activation in mononuclear cells that may represent T cells, macrophages or dendritic cells." (PMID 23825651, 2013). "In the normal breast, Notch1 is thought to play a role in the early luminal progenitor cells rather than stem cells and an analogous situation may, therefore, exist in cancers, whereby oestrogen exerts its effects on early differentiation progenitors of the CSC, rather than the CSC itself." (PMID 23497505, 2013). "However, the combined siRNA-mediated knockdown of Klf4 and Sp3 resulted in consistent up-regulation of Notch1 expression in both HKCs and cancer cells (HeLa and SCC13 cells), with the concomitant knock-down of Sp1 having no additional effects (C and data not shown)." (PMID 20442780, 2010). "However, Notch1 expression can also become aberrantly suppressed by Klf4 during cancer development." (PMID 20442780, 2010). "For the first time, we demonstrate that pregnancy-level PRL directly enhances JAK2/STAT3 and JAG1/NOTCH1 signaling in CRC cells, promoting epithelial-mesenchymal transition (EMT) and cancer stem-like protein expression." (PMID 41501898, 2026). "Patients with hypopharyngeal SCC who exhibit concurrent expression of integrin beta 1 (ITGB1) and neurogenic locus notch homolog protein 1 (NOTCH 1) protein experience significantly poorer survival rates, potentially through the regulation of cancer stemness." (PMID 41466485, 2026). "Overexpression of ZNF671 suppresses the expression of Notch1 and its downstream targets, whereas ZNF671 silencing enhances Notch pathway activation, promoting cancer cell proliferation and invasion—effects that can be reversed by Notch inhibition." (PMID 41602823, 2026). "In vitro data was then used to link pregnancy levels of PRL to increased JAK2/STAT3 and JAG1/NOTCH1 signaling resulting in increased epithelial-to-mesenchymal transition (EMT) and cancer cell stem-like protein expression." (PMID 41501898, 2026). "MFAP2 contributes to cancer progression and drug resistance by activating the FAK-AKT signaling pathway, Notch1 pathway, and Wnt/β-catenin signaling pathway." (PMID 40228435, 2025). "Notch1 has a role in maintaining CSC stemness in TNBC, and inhibiting this signal not only has an inhibitory effect on this cancer subtype but also increases its chemosensitivity." (PMID 39882028, 2025). "Importantly, selection acting to elevate mutational burden in normal tissue is a poor predictor of cancer driver activity, with gene mutations being strongly selected in host tissue but almost absent in cancers, such as NOTCH1 in the oesophagus, and vice versa." (PMID 39920335, 2025). "Expression level data of Notch1-4 and DLL4 in cell lines were downloaded from the CCLE (cancer cell line encyclopedia) database." (PMID 39951484, 2025).
cancer (continued). "Additionally, the identification of NOTCH1 aberrations in hematopoietic stem cells of CLL patients highlighted the contribution of NOTCH1 in driving the clonal expansion of cancer cells, suggesting that NOTCH1 inhibition could potentially lead to CLL regression or contrasting RT progression." (PMID 40113912, 2025). "This is achieved through the impairment of mitochondrial function and the inhibition of key signaling pathways, namely, Notch1 and JAK1/STAT3, which are critical drivers of cancer progression." (PMID 40019515, 2025). "Notch pathway negatively impacts the activity of the Wnt pathway in most cancers; Wnt can also impact the expression of DLL1, HES1 and NOTCH2 on the protein level, while β-catenin can also interact with NOTCH1 and reduce its ubiquitination." (PMID 40002854, 2025). "From other cancers it is also reported that besides USP28, the deubiquitinases USP7, USP8, USP10 and USP11 interact with NICD and regulate NOTCH1 signaling." (PMID 40456839, 2025). "To further elucidate the role of Notch1 signaling in PLAU-mediated cancer progression, we constructed PDAC cells with stable overexpression and knockdown of Notch1 (via lentiviral transduction)." (PMID 39834857, 2025). "Increased CCL2 expression in activated fibroblasts required STAT3 activation by diverse BC-secreted cytokines, and in turn, induced NOTCH1 expression and the CSC features in BC cells, constituting a cancer–stroma–cancer signaling circuit." (PMID 39335478, 2024). "When comparing NACT-treated samples with untreated ones in cancer patients the expression of TMEM51, NOTCH1, EEPD1, MAFB, and HLA-DRB5 remained increased in monocytes of treated patients." (PMID 39315092, 2024). "Among 36 genes, MMP1, HSP90B1, PTK2, MMP3, NOTCH1 and CDH5 had higher methylation status at pan-cancer level." (PMID 38694917, 2024). "We also examined the Notch1/Hes1 signaling pathway, which is known to participate in the EMT of cancer cells." (PMID 38166853, 2024). "First, the inhibition of Notch1 expression in the H69AR cell line increases the expression of MRP-1, increasing cancer chemo-resistance." (PMID 40034926, 2024). "In summary, these studies conclude that NOTCH1, through its activation product NICD, forms a necessary link in the RAB4A signaling axis upstream of RAC1 and SOX2 in promoting the cancer cell stemness/self-renewal property." (PMID 39463384, 2024). "So far, we have demonstrated that NUMB, NOTCH1, and RAC1 regulate cancer cell self-renewal downstream of RAB4A, and that this signaling chain controls the transcription of SOX2." (PMID 39463384, 2024). "Other teams showed that increased expression of CRNDE stimulates cancer cells to divide, invade other tissues, and metastasize by activation of the Wnt/ß-catenin, PI3K/AKT/mTOR, Ras/MAPK and Notch1 pathways." (PMID 38673965, 2024). "The findings confirmed that RAB4A positively controls levels of NOTCH1 and SOX2, and negatively of NUMB, in these cancer cells." (PMID 39463384, 2024). "Using in vitro and in vivo studies, we show that RAB4A, as the upstream regulator, relays signal stepwise to NUMB, NOTCH1, RAC1, and then SOX2 to control the self-renewal property of multiple cancer cells of diverse tissue origins." (PMID 39463384, 2024). "In conclusion, these studies in both RAB4A-high and RAB4A-low cancer cells demonstrate that RAC1 is upstream of SOX2 in the RAB4A regulation of cancer stemness, while the order of regulation among RAC1, NUMB, and NOTCH1 are yet to be defined." (PMID 39463384, 2024). "Even though Notch1 protein expression showed promising results in inhibiting the growth of the SCLC, other studies on other cancer types demonstrated opposite results." (PMID 40034926, 2024).
cancer (continued). "The correlation between PTEN and RBPJ, a vital protein of the Notch-1 pathway, was also confirmed using the GEPIA (GEPIA (Gene Expression Profiling Interactive Analysis) (cancer-pku." (PMID 38733531, 2024). "Importantly, biochemical and bioinformatic analyses led to the identification of multiple available drugs that may have therapeutic utility against Notch1-dependent cancers, although substantial research is needed to assess whether and how they affect Notch1 biological function." (PMID 38043798, 2024). "Our clinical sample analysis revealed that the expression of Notch pathway receptor Notch1 and ligand DLL4 was significantly higher in HCC tissues compared to para-cancer tissues." (PMID 38650927, 2024). "By shedding light on previously unexplored cancer types, our study revealed the complex nature of ASPH-mediated Notch1 pathway regulation, but more importantly, highlighted the heterogeneous response of different cancer types to ASPH inhibition." (PMID 38817852, 2024). "This is achieved by inhibiting the Notch1 and STAT3 signaling pathways, which are also involved in cancer cell proliferation." (PMID 38731894, 2024). "The in vitro study of the signaling chain whereby RAB4A impacts cancer cell stemness has demonstrated that NUMB, NOTCH1, RAC1, and SOX2 are essential in mediating the regulatory effects of RAB4A on CSCs in multiple cancer cell lines of diverse tissue origins." (PMID 39463384, 2024). "Although cancer invasion and metastasis promoted by EMT are the typical features of malignant tumors, our analysis revealed that in the patients with enriched TGFβ signaling, lower enrichment of JAG1- or NOTCH1-DEGs led to worse prognosis." (PMID 39074091, 2024). "Overall, given that the activity of both PIM kinases and Notch1 plays a crucial role in driving tumor growth and progression, attempts are being made to target or co-target these molecules for targeted cancer therapy, which may result in new and potent cancer treatment strategies." (PMID 38339286, 2024). "In colorectal cancer, downregulation of miR-34 which targets NOTCH1 and JAG1 involved in cancer stem cell acquisition resulted in increased IL-6 signaling, which led to EMT and cancer metastasis." (PMID 37460910, 2023). "Important endocrine system and cancer-related genes and pathways appear to be dysregulated among WTC-exposed individuals; these include WRN, BRCA1, NOTCH1, and NTRK1, among others." (PMID 38131903, 2023). "Downregulation of ST6GAL1 decreases Jagged1, DLL-1, Notch1, Hes1, Hey1, MMPs and VEGF, and suppresses cancer cell proliferation, migration and invasion." (PMID 37256139, 2023). "Contrary to the expected oncogenic roles of Notch1 and c-Myc, the biological functions of SIRT1 in cancer remain controversial." (PMID 37960146, 2023). "In this study, a variety of assays demonstrated the successful inhibition of the NOTCH1 pathway by CAD204520, resulting in specific anti-cancer activity." (PMID 37833915, 2023).